FGFR3 (fibroblast growth factor receptor 3)
Diseases named in the same sentence as FGFR3 in open-access papers (continued):
Sharing a sentence is not in itself a finding about the gene and the disease.
insomnia (1 paper, 2020). A sleep disorder characterized by difficulty in falling asleep and/or remaining asleep. "In conclusion, the current comprehensive study provides multiple lines of evidence for supporting DALRD3, LDHA, HEBP2, TEX264, and FGFR3 as insomnia-associated genes whose abnormal expression level may convey risk to insomnia." (PMID 32830860, 2020).
intervertebral disc disease (1 paper, 2025). "Data emerging from these preclinical models and other sources now point to intervertebral disc disease being a primary manifestation of ACH and other FGFR3-opathies." (PMID 40178985, 2025).
intestine cancer (1 paper, 2022).
leukoplakia (1 paper, 2015). A white patch or plaque on a mucous membrane that cannot be characterized clinically or pathologically as any other disease. "The present study was undertaken to analyze expression of FGF-2 and its receptors FGFR-2 and FGFR-3 in 72 PMOLs, 108 OSCC and 52 healthy controls, and their role in risk assessment for malignant transformation of Leukoplakia (LKP) and Oral submucous fibrosis (OSMF) to OSCC." (PMID 26465941, 2015).
liver disease (1 paper, 2018). "We describe FGFR3 overexpression in 15% of CRC patients with oligometastatic liver disease as a prognosticator for poor outcome." (PMID 30181810, 2018).
lymphedema (1 paper, 2021). Excess fluid collection in tissues, causing swelling. "In addition, our results also indicate that FGFR3 might be a therapeutic target for lymphatic dysfunction-related diseases such as human lymphedema." (PMID 34282140, 2021).
Maffucci syndrome (1 paper, 2019). Maffucci syndrome is a very rare genetic bone and skin disorder characterized by multiple enchondromas, leading to bone deformities, combined with multiple dark, irregularly shaped hemangiomas or less commonly lymphangiomas. "In a genetic study of various breast lesions, mutated tubular adenomas showed primarily mutations in MET and FGFR3, whereas enchondromas in Maffucci’s syndrome have been known to harbour isocitrate dehydrogenase (IDH1 and 2) mutations." (PMID 31585326, 2019).
mismatch repair deficiency (1 paper, 2020). "Subsets of the patients with actionable fibroblast growth factor receptor 3 (FGFR3) aberrations (4%) and mismatch repair deficiency (4%) were potentially eligible for precision medicine." (PMID 32726920, 2020).
mood disorder (1 paper, 2015). A cognitive disorder a disturbance in which the person's mood is hypothesized to be the main underlying feature. "For instance, FGF1, FGF2, FGF receptor (FGFR) 2 and FGFR3 were significantly down-regulated in the frontal cortex of MDD patients, which strongly suggests that FGF signaling must be disrupted in mood disorders." (PMID 26537115, 2015). "Specifically, FGF1, FGF2, FGF receptor (FGFR) 2 and FGFR3 were down-regulated in the frontal cortex of MDD patients, which strongly suggests that FGF signaling must be disrupted in mood disorders." (PMID 26537115, 2015).
motion sickness (1 paper, 2023). sympton caused by motion, as sea sickness, train sickness, car sickness, air sickness, or space motion sickness. "We found that meclizine, which is an over-the-counter drug for motion sickness, inhibited the fibroblast growth factor receptor 3 (FGFR3) gene using a drug repositioning strategy, and meclizine 1 and 2 mg/kg/day promoted bone growth in a mouse model of ACH." (PMID 37428729, 2023).
multicystic dysplastic kidney (1 paper, 2011). Multicystic dysplastic kidney (MCDK) is a congenital anomaly of the kidney and urinary tract (CAKUT) in which one or both kidneys (unilateral or bilateral MCDK respectively) are large, distended by multiple cysts, and non-functional. "The molecular events involved in multicystic dysplastic kidneys, in general, remain to be elucidated, though studies have suggested involvement of WNT-1, FGFR3, and PAX2." (PMID 21995344, 2011).
myocardial ischemia (1 paper, 2013). A disorder of cardiac function caused by insufficient blood flow to the muscle tissue of the heart. "As FGF21 interacts with all known protein tyrosine kinase-coupled FGFRs, including FGFR1, FGFR2, FGFR3, and FGFR432, 36, 37, we tested the expression of these FGFRs in cardiomyocytes from wild-type mice with and without myocardial ischemia/reperfusion injury." (PMID 24067542, 2013).
pancreatic endocrine carcinoma (1 paper, 2013). An aggressive, high-grade and poorly differentiated carcinoma with neuroendocrine differentiation that arises from the pancreas. "In tissue microarrays, when compared to FGFR3 signal intensity in normal pancreas (high in islets, weak in ducts), about 70% of the pancreatic endocrine carcinomas showed partial or total loss of FGFR3 signal." (PMID 23902722, 2013).
papillary carcinoma (1 paper, 2017). A malignant epithelial neoplasm characterized by a papillary growth pattern. "The most prevalent genetic alterations reported in papillary carcinoma includes the deletions of chromosome 9, point mutations in fibroblast growth factor receptor 3 (FGFR3) and alpha catalytic subunit of phosphatidylinositol 3-kinase (PIK3CA)." (PMID 28589430, 2017).
papillary urothelial neoplasm (1 paper, 2012). "Even more, there was report showed that Strong immunohistochemical expression of FGFR3, a superficial staining pattern of CK20, and a low proliferative activity define those papillary urothelial neoplasms of low malignant potential that do not recur." (PMID 23082147, 2012).
papilloma (1 paper, 2023). A benign epithelial neoplasm that projects above the surrounding epithelial surface and consists of villous or arborescent outgrowths of fibrovascular stroma. "The result showed that papilloma carried higher mutation rate of genes, such as MPRIP, HRAS, and MAP3K1, while PUC carried a higher mutation rate of genes, such as FGFR3 and PPFIBP1 (Fisher’s exact test, p < 0.05)." (PMID 37704624, 2023).
pediatric cancers (1 paper, 2025). "Using a broad search of all pediatric cancers, we observed the rates of alterations of the FGFR1, FGFR2, FGFR3, and FGFR4 genes in pediatric cancers to be 0.5%, 0.1%, 1.1%, and 0.8%, respectively." (PMID 40510032, 2025).
Pfeiffer syndrome type 3 (1 paper, 2019). Pfeiffer syndrome type 3 (PS3) is a severe type of Pfeiffer syndrome (PS), characterized by bicoronal craniosynostosis, severe associated functional disorders, and hand, foot and elbow abnormalities. "The de novo FGFR3 p.Ala391Glu change identified was unexpected since pigmentary skin irregularities have not been observed in CS‐39 to date, and the craniofacial phenotype suggested Pfeiffer syndrome type 3." (PMID 31016899, 2019).
pilocytic astrocytoma (1 paper, 2017). Pilocytic astrocytoma is a rare subtype of low-grade glioma of the central nervous system characterized by a well circumscribed, often cystic, brain tumor with a discrete mural nodule and long, hair-like projections that extend from the neoplastic astrocytes. "In pilocytic astrocytoma, moderate-to-strong FGFR3 staining was observed predominantly in non-pediatric patients." (PMID 28468611, 2017). "In pilocytic astrocytomas, moderate-to-strong FGFR3 expression was detected predominantly in non-pediatric patients." (PMID 28468611, 2017). "In non-diffuse gliomas, FGFR1 alterations are commonly present in a subgroup of pilocytic astrocytomas that lack other typical MAPK pathway alterations, but FGFR1 and FGFR3 expression levels have not been systematically evaluated." (PMID 28468611, 2017).
Pleural effusion (1 paper, 2025). The presence of an excessive amount of fluid in the pleural cavity. "Following disease progression on lorlatinib, next-generation sequencing analysis of pleural effusion identified an acquired ROS1 L2086F resistance mutation, accompanied by a concurrent mTOR mutation and FGFR3 gene amplification." (PMID 40826797, 2025). "NGS analysis of pleural effusion revealed a complex resistance profile, including the original CD74-ROS1 fusion, an acquired ROS1 L2086F resistance mutation, an mTOR (p.E2419K) mutation, and FGFR3 gene amplification." (PMID 40826797, 2025).
polydactylism (1 paper, 2022). "PCSCs were isolated from the ring of La-Croix extracted from polydactylism patient and identified through immunohistochemically staining using anti-FGFR-3 antibodies." (PMID 35573235, 2022).
polyneuropathy (1 paper, 2021). A disease or disorder affecting more than one nerve. "Overall, this study describes the clinical and electro diagnostic findings in a well-defined group of patients with anti-FGFR3 antibody-related polyneuropathy." (PMID 33588772, 2021).
pterygium (1 paper, 2017). A wedge-shaped fibrovascular lesion arising from the bulbar conjunctiva and extending to the cornea. "Further investigation revealed that mTORC1 activation is significantly associated with inhibition of autophagy and FGFR3 in pterygium." (PMID 28779179, 2017). "On the basis of these data, we propose that loss of FGFR3 in pterygium epithelial cells may result from mTORC1 activation, thus representing a mechanism for aberrant proliferation during pterygium growth and development." (PMID 28779179, 2017). "On the basis of immunofluorescence analysis, FGFR3 was found to be expressed across the entire width of the epithelial layer in normal conjunctiva, whereas FGFR3 was scarcely detected in pterygium." (PMID 28779179, 2017). "Our findings establish a novel link between mTOR, autophagy, FGFR3 and the aberrant apoptosis and hyperproliferation that occurs during the growth and development of pterygium." (PMID 28779179, 2017). "We propose a pathway in which mTORC1 activation downregulates autophagy and FGFR3 in pterygium epithelial cells, thus consequently inhibiting apoptosis, stimulating cell proliferation, and promoting pterygium growth and development." (PMID 28779179, 2017). "mTORC1 activation promotes pterygium growth and development via targeting autophagy and FGFR3, thus inhibiting apoptosis and stimulating cell proliferation." (PMID 28779179, 2017). "we found that p73, a transcription factor for FGFR3 that is regulated by mTORC117, 18, was also downregulated in pterygium compared with normal conjunctiva, on the basis of western blot analysis." (PMID 28779179, 2017). "In normal conjunctiva, FGFR3 was expressed across the entire width of the epithelial layer, whereas in pterygium, FGFR3 was scarcely detected." (PMID 28779179, 2017). "Together, these results indicated that mTORC1 activation in pterygium epithelial cells negatively regulates FGFR3 through inhibition of p73." (PMID 28779179, 2017). "mTORC1 signalling - control of autophagy and FGFR3 is a critical regulator of pterygium epithelial cell metabolism and a potential target for pterygium treatment." (PMID 28779179, 2017). "Rapamycin enhanced p73 and FGFR3 expression levels in pterygium epithelial cells, whereas p73 siRNA inhibited rapamycin-induced FGFR3 expression." (PMID 28779179, 2017). "mTORC1 also negatively regulates fibroblast growth factor receptor 3 (FGFR3) through inhibition of p73, thereby stimulating cell proliferation in pterygium." (PMID 28779179, 2017). "In this study, we estimated mTOR signalling and demonstrated the roles of autophagy and fibroblast growth factor receptor 3 (FGFR3) in aberrant apoptosis and hyperproliferation in pterygium." (PMID 28779179, 2017). "In this study, we found that mTORC1 activation decreased FGFR3 expression whereas rapamycin increased FGFR3 expression in pterygium epithelial cells." (PMID 28779179, 2017). "Moreover, FGFR3 mRNA levels were also markedly decreased in pterygium compared with normal conjunctiva." (PMID 28779179, 2017). "Interestingly, we observed significant inhibition of FGFR3 in pterygium." (PMID 28779179, 2017). "Investigation into the molecular mechanisms of mTORC1 and FGFR3 revealed that rapamycin administration rescued the FGFR3 expression and the negative effect of FGFR3 on proliferation of pterygium epithelial cells." (PMID 28779179, 2017). "However, no studies have focused on the effect of FGFR3 in pterygium epithelial cells." (PMID 28779179, 2017).
renal pelvis tumors (1 paper, 2023). "Taken together, these data support the oncogenic role of up-regulated FGFR3 expression in the development of renal pelvis tumors in both Asian and Caucasian populations." (PMID 36675289, 2023). "Overall, marked FGFR3 up-regulation could be seen in the development of renal pelvis tumors in both Asian and Caucasian populations." (PMID 36675289, 2023).
salivary gland carcinoma (1 paper, 2025). A carcinoma that arises from the major or minor salivary glands. "The FGFR3::TACC3 fusion has been reported in one of 27 metastatic salivary gland carcinomas subjected to next-generation sequencing in one study." (PMID 39387893, 2025).
Sensorimotor neuropathy (1 paper, 2021). "We performed a retrospective chart review to assess the clinical characteristics of patients with sensory or sensorimotor neuropathy related to FGFR3 antibodies." (PMID 33588772, 2021).
silicosis (1 paper, 2024). Silicosis is a respiratory disease caused by breathing in (inhaling) silica dust. "The qPCR results showed that FGFR3 expression was increased in the lung of mice with silicosis compared with those in the control group, and decreased after exosome treatment." (PMID 39684337, 2024). "FGFR3, a target of miR-99a-5p, showed increased expression both in vitro and in vivo silicosis models." (PMID 39684337, 2024). "In our study, we attempt to identify whether the downregulation of miR-99a-5p elevates FGFR3 to promote fibroblasts transdifferentiation in silicosis." (PMID 39684337, 2024). "Particularly, MSC-derived exosomes deliver miR-99a-5p to fibroblasts and inhibit fibroblast activation by suppressing FGFR3 and downstream MAPK signalling pathway, which indicates a potentially effective treatment for silicosis." (PMID 39684337, 2024). "Furthermore, we showed that exosomal miR-99a-5p regulated fibroblast activation through the FGFR3 and downstream MAPK signalling pathway, thereby alleviating the pathological progression of silicosis." (PMID 39684337, 2024). "Nevertheless, the regulatory mechanism of FGFR3 in silicosis is still not clear." (PMID 39684337, 2024). "Importantly, MSC-derived exosomes deliver miR-99a-5p to fibroblasts and inhibit fibroblast transdifferentiation by targeting FGFR3 and regulating MAPK signalling, which indicates that they could be promising candidates for the development of silicosis therapies." (PMID 39684337, 2024).
skull base meningioma (1 paper, 2019). A meningioma that arises from the skull base. "Among our findings were the identification of a TERTp mutation and the first report of FGFR3 mutations that may represent biomarkers for the identification of skull base meningioma patients with a favorable prognosis." (PMID 31565188, 2019).
squamous cell cervical carcinoma (1 paper, 2005). "Distribution of HPV types associated with FGFR3 mutated tumors was rather different than the expected distribution in squamous cell cervical carcinoma." (PMID 15869706, 2005).
squamous intraepithelial lesions (1 paper, 2005). "The rate of FGFR3 mutation in invasive cervical carcinoma is significantly different from the one in squamous intraepithelial lesions (P = 0.036, chi-square test)." (PMID 15869706, 2005).
tauopathy (1 paper, 2024). Neurodegenerative disorders involving deposition of abnormal tau protein isoforms (tau proteins) in neurons and glial cells in the brain. "To determine whether FGFR3 is required for the uptake of AD-associated pathogenic tau in neurons, we exogenously injected preformed synthetic human tau fibrils (PFFs) with AAV9-siFGFR3 into tauopathy model mice, which are known to be internalized and initiate tauopathy with tau propagation." (PMID 38951140, 2024).
tonsil (1 paper, 2023). "Of note, FGFR3 has been identified as a common variant, particularly in HPV-positive tonsil/base of tongue cancers, where FGFR3 mutations have indicated worse prognosis of patients." (PMID 36979829, 2023). "In HPV-associated and -unrelated TCGA tonsil cancer data, the tendency for CDKN2A (0% vs. 16.7%, respectively), FGFR3 (6.3% vs. 0%, respectively), and RB1 (9.4% vs. 7.9%, respectively) expression was comparable to that observed in our cohort." (PMID 36979829, 2023).
transitional cell tumor (1 paper, 2015). "In the group of patients where a transitional cell tumor was confirmed at histopathological evaluation, urine DNA was positive for one or more markers in 29 out of 31 cases (94%), including 19 with FGFR3 mutation (61%)." (PMID 26151138, 2015).
urothelial carcinoma of the renal pelvis (1 paper, 2020). "Indeed, PIK3CA mutations are considered as an early genetic alteration associated with FGFR3 mutations in superficial papillary NMIBC and the activation of the PI3K/AKT pathway is identified to induce urothelial carcinoma of the renal pelvis." (PMID 32333246, 2020).
Venous malformation (1 paper, 2022). A vascular malformation resulting from a developmental error of venous tissue composed of dysmorphic channels lined by flattened endothelium and exhibiting slow turnover. "We found the same GLMN variant c.108C > A (p.(Cys36*)), both in a patient with an AVM and in a patient with venous malformations in association with a somatic KRAS variant c.35G > A (p.(Gly12Asp)) and a somatic FGFR3 CNV, respectively." (PMID 35807022, 2022).